RN7SKP175 (RN7SK pseudogene 175)
Gene: Miscellaneous RNA gene on chromosome 8 (143,542,110 to 143,542,398, forward strand). Ensembl gene ENSG00000275558.
Homologues: Orthologues: chimpanzee 7SK (99% identical). Paralogues in human: 7SK (87% identical), RN7SKP187 (80% identical), RN7SKP118 (80% identical), RN7SKP48 (79% identical), RN7SKP185 (78% identical), RN7SKP174 (78% identical), RN7SKP178 (78% identical), RN7SKP227 (77% identical), RN7SKP76 (77% identical), RN7SKP160 (75% identical), RN7SKP80 (75% identical), RN7SKP203 (74% identical), and 284 more.